PARP1 (poly(ADP-ribose) polymerase 1)
Diseases named in the same sentence as PARP1 in open-access papers (continued):
Sharing a sentence is not in itself a finding about the gene and the disease.
pancreatic cancer (continued). "Therefore, the approach of targeting PARP-1 is emerging as a promising therapeutic strategy for targeting the pathogenesis in pancreatic cancer." (PMID 33805293, 2021). "Hence, it is also an important research area to focus on the transcriptional regulation by PARP-1 in pancreatic cancer cells." (PMID 33805293, 2021). "However, the application of PARP-1 inhibitors targeting pancreatic cancer is still in its infancy, and there exists a need to remove several negative factors." (PMID 33805293, 2021). "Therefore, we reasoned that blocking PARP1 activity in addition to KP372-1 treatment should further augment cytotoxicity of pancreatic cancer cells." (PMID 33214574, 2020). "Furthermore, VEDT was found to inhibit c-FLIPs expression and induce caspase-8-dependent apoptosis in pancreatic cancer cells, followed by caspase-3 and PARP1 cleavage in a time-dependent manner." (PMID 31367187, 2019). "As NAD+ in depleted by FK866 treatment, PARP-1 could become inactive and thus increase the effect of gemcitabine on pancreatic cancer cells." (PMID 27462772, 2016). "Summary of APE1, XRCC1, and PARP1 studies in pancreatic cancer." (PMID 25988138, 2015). "Additionally, PARP-1 overexpression inhibits the recruitment of death-inducing signaling complex in pancreatic cancer cells, offering the ability to resist TNF-related apoptosis-inducing ligand (TRAIL) therapy." (PMID 26314963, 2015). "Killing of pancreatic cancer cells by CDDO-Me was associated with an increase in annexin-V-FITC binding, cleavage of PARP-1 and procaspases, mitochondrial depolarization, release of cytochrome C, and inhibition of prosurvival/progrowth signaling proteins such as p-Akt, NF-κB and p-mTOR." (PMID 21799944, 2010). "Thus, increase in annexin V-FITC-binding and the cleavage of PARP-1 suggest that the growth inhibitory activity of CDDO-Me against pancreatic cancer cells is due to induction of apoptosis." (PMID 21799944, 2010). "However, the role of PARP-1 as a prognostic marker of pancreatic cancer is still controversial." (PMID 35453444, 2022). "The PARP1 and PARP2 biology observed for the CRC cases in this study differs significantly from their established status in breast, ovarian, prostate and pancreatic cancers." (PMID 40573300, 2025). "Through co-immunoprecipitation, we observed an interaction between PARP1 and TOPBP1 in pancreatic cancer cell lines, indicating the involvement of complex molecular regulatory mechanisms in the combined effects of olaparib with shTOPBP1 or ATRi." (PMID 39920847, 2025). "Consistently, high DDX5 expression in pancreatic cancer tissues was correlated to high CD24 expression, while the PARylation activity of PARP1 was inversely correlated with CD24 expression." (PMID 37596619, 2023). "FoxO1, encoding a transcription factor, was up-regulated in its mRNA and protein levels in the PARP1-KO Ewing sarcoma RD/KO1, Cri/KO, and SK/KO1 cells and pancreatic cancer CAPAN1/KO cells." (PMID 31992690, 2020). "Regarding the colon and pancreatic carcinoma cell lines, to try to more precisely define the cell death mechanisms evoked by CLytA-DAAO, we determined the effect of PARP-1 inhibition." (PMID 33198289, 2020). "Martínez-Bosch and colleagues proved that PARP-1 upregulates MDM2, VEGFR1, and MMP28, accelerating tumor proliferation and angiogenesis in pancreatic cancer." (PMID 26314963, 2015).
pancreatic cancer (continued). "As additional controls, the indicated pancreatic cancer cells were treated with ABT-888, a poly(ADP-ribose) polymerase 1 and 2 (PARP1/2) inhibitor, or MK-1775, a Wee1 kinase inhibitor and then exposed to IR." (PMID 25344910, 2014). "Furthermore, co-targeting PARP1 (with talazoparib) and CD24 (with anti-CD24 mAb) elicited synergistic antitumor effects in human pancreatic cancer animal models (Fig. 3C2)." (PMID 37596619, 2023). "In this sense, the augmented detection of PARP-1, NOX1 observed in patients with pancreatic cancer who exhibited a lower survival in our study could be attributed to this fact." (PMID 35453444, 2022). "In particular, considering the genetic characteristics of the majority of pancreatic cancers using non-HR pathways and achieving significant clinical benefits by targeting PARP-1 are also of significant potential." (PMID 33805293, 2021). "Besides inhibiting SIRT1 and PARP1, NAM has shown to inhibit the oncogenic KRAS/AKT pathway in skin and pancreatic cancers, modulate the expression of Myc oncogene in bladder cancer, and suppress IGF-1 in HCC." (PMID 32245130, 2020). "PARP-1 is overexpressed in different types of cancer, including prostate, pancreatic, and breast, and it has been reported that decreased expression of PARP-1 inhibited cell proliferation and induced apoptosis in pancreatic cancer cells." (PMID 30402124, 2018). "Additionally, we have recently reported that TRA-8-induced DISC recruitment of PARP-1 regulates caspase-8 activation in the DISC, which is accompanied by enhanced sensitivity of pancreatic cancer cell to TRA-8-induced apoptosis." (PMID 26320171, 2015). "Whether inhibition of growth of pancreatic cancer cells by CDDO-Me was due to induction of apoptosis was investigated by measuring the binding of annexin V-FITC and cleavage of PARP-1." (PMID 21799944, 2010). "Nonetheless, PARP1 is more abundant in the nucleus, suggesting that the current clinical success of PARPi is heavily reliant on DNA repair inhibition and synthetic lethality, rather than the inhibition of cytoplasmic PARP1-mediated proliferation and survival, in pancreatic cancer." (PMID 34440228, 2021). "Interestingly, it has been noted that the anticancer effects of NAMPTis in pancreatic cancer are not influenced by either SIRT1 or PARP1, indicating that the impact of NAMPT on PARP1 or sirtuins may vary depending on the type of cancer." (PMID 38116009, 2023). "Furthermore, the proliferation of MiaPaCa-2 pancreas cancer cells, PC-3 prostate cancer cells (IC50: 32 μM, 24 h), and dRLh-84 hepatic cancer cells (IC50: 80–100 μM, 24 h) was suppressed by γ-T3, most likely via cleavage of PARP-1, and caspases 3, 7, 8, and 9 and induction of autophagy." (PMID 32372948, 2020).
glioma (70 papers, 2010 to 2026). A benign or malignant brain and spinal cord tumor that arises from glial cells (astrocytes, oligodendrocytes, ependymal cells). "In a number of cases, failures in glioma therapy are closely associated with the DNA repair system, particularly PARP1, making it a high-priority therapeutic target." (PMID 41304780, 2025). "BLM deficiency affects responses of glioma cells to chemotherapeutics targeting PARP1 dependent pathways." (PMID 37169803, 2023). "Follow-up studies confirmed the radiosensitizing effect of PARP1 inhibitors on S-phase cells not only in fibroblasts carrying capillary ataxia mutation genes but also in human lung, breast, glioma, and head and neck cancer cells." (PMID 38111536, 2023). "Consistent with previous findings in established cell lines, exposure of primary glioma stem-like cells (GSCs) to therapeutically relevant frequency of TTFields (200 kHz) caused DNA damage and activated both PARP1 and ATR signalling pathways." (PMID 37777579, 2023). "We had already published that indomethacin caused proteolytic degradation of PARP-1 and a reduction of Akt phosphorylation in glioma cells." (PMID 31952288, 2020). "There have been some investigations into the prognostic markers for gliomas including Poly (ADP-ribose) polymerase-1 (PARP-1) Val762Ala polymorphism." (PMID 31186453, 2019). "Another study provided evidence that the PARP1-associated DNA reparation pathway was compromised in IDH-mutant gliomas due to decreased NAD+ content; importantly, targeting the PARP1 DNA repair pathway markedly sensitized IDH1-mutant gliomas to temozolomide." (PMID 30279357, 2018). "For example, DNA damage in human glioma U373 cells treated with Limoniastrum guyonianum polyphenolic extract was associated with the PARP1 cleavage." (PMID 30171426, 2018). "By contrast, the PARP-1 V762A polymorphism was significantly associated with a decreased risk of glioma in three genetic models." (PMID 24853559, 2014). "Pediatric high grade glioma, medulloblastoma and ependymoma gene expression profiling revealed that high PARP1 expression is associated with poor prognosis." (PMID 22184287, 2011). "In a case-control study, PARP-1 polymorphism has been associated with reduced risk of adult glioma in men." (PMID 20196871, 2010). "Also, gene expression profiling of pediatric high-grade glioma, ependymoma, and medulloblastoma showed that high expression of PARP1 has been linked to a poor prognosis." (PMID 35873570, 2022). "Therefore, it is hypothesized that a PARP1-specific aptamer would exhibit dual action, enhancing the DNA-damaging effects of radiation and modulating signaling cascades that underlie glioma aggressiveness and radiation-induced invasion." (PMID 41304780, 2025). "This suggests that replication associated PARP1 activation may be suppressed in glioma." (PMID 34806016, 2021). "The mean nuclear IRS of PARP1 was significantly higher in gliomas from BRCA2 GV carriers than in those from ATM GV carriers." (PMID 41546701, 2026). "All BRCA2 GVs identified here were LoF variants resulting in a reduced BRCA2 expression and an increased PARP1 expression, on average, in glioma sections compared to gliomas from non-BRCA2 GV carriers, thus impacting the molecular tumor phenotype." (PMID 41546701, 2026). "These cells expressing LMNA, PRKDC, and PARP1 transcripts are molecularly more dedifferentiated glioma stem-like cells, specifically OPC-like cells." (PMID 41271669, 2025). "Deoxypodophyllotoxin (DPT) induces parthanatos in glioma cells by excessive ROS generation, PARP1 upregulation, and AIF nuclear translocation." (PMID 40166425, 2025).
glioma (continued). "Inhibiting PARP-1 has been a strategy for developing new drugs to overcome the resistance of glioma cells to radiation- or chemotherapy-induced apoptosis." (PMID 38304870, 2024). "Studies propose that EZH2 can enhance glioma resistance to temozolomide (TMZ) by regulating the FADD/PARP1 axis." (PMID 39069522, 2024). "PARP-1, also known as poly (ADP-ribose) synthase 1 or poly (ADP-ribose) transferase 1, exhibits higher basal levels in glioma cells compared to neurons and is positively associated with glioma malignancy and poor patient survival." (PMID 38304870, 2024). "Inhibiting PARP-1 has been a strategy for developing new drugs to overcome the resistance of glioma cells to radiotherapy or chemotherapy-induced apoptosis." (PMID 38304870, 2024). "We found that BLM deficient glioma cells become resistant to the combined TMZ and PARP1 inhibitor treatment and respond with polyploidy or cellular senescence." (PMID 37169803, 2023). "The aim of present study was to elucidate the role of expression deregulations of mitochondrial sirtuin genes and co-expression with their associated proteins (SOD1, SOD2, OGG1-2α, PARP1, GDH and HIF1α) in glioma." (PMID 36809279, 2023). "In this study we explored the downstream signal of activated PARP1 to induce nuclear translocation of AIF in DPT-triggered glioma cell parthanatos." (PMID 37186123, 2023). "Variations in genes involved in DNA repair, cell cycle, metabolism, and inflammation pathways have been recognized as a key basis of inherited glioma susceptibility, such as PRKDC, XRCC1, PARP1, ERCC1, ERCC2, EGF, and IL13." (PMID 36733406, 2023). "interestingly, PARP1 agonists such as β-lapachone and deoxypodophyllotoxin are reported to trigger parthanatos in hepatoma carcinoma cells and glioma cells through indirectly activating PARP1 via induction of excessive ROS." (PMID 35806303, 2022). "Regarding this, it is worth noting that ZIKV protein NS3 itself potently activates a nuclear poly (ADP-ribose) polymerase, PARP1, in HeLa and glioma cells that results in NAD+ depletion and cell death at 48 h post-treatment in the former." (PMID 35493328, 2022). "The cell death of the glioma, which is caused by H2O2, is accompanied by PAR polymer cytoplasmic formation, PARP1 over-activation, and AIF nuclear translocation." (PMID 35806303, 2022). "Inhibition of PARP-1 can improve the prognosis of glioma and promote chemoradiotherapy sensitization, which offers new ideas for treating glioma." (PMID 36092717, 2022). "This was consistent with the findings suggesting that ATRX knockout can suppress DNA damage repair by regulating ATM pathway or mediating PARP1 instability to sensitize glioma cells to TMZ treatment." (PMID 35720326, 2022). "First, we systematically analyzed the influence of PARP-1 on DNA damage repair, prognosis, and chemoradiotherapy sensitization of glioma." (PMID 36092717, 2022). "In our study, OSW-1 was capable of significantly increasing the apoptotic cell ratio of glioma cells, and discovered that the expression level of cleaved caspase-3/9 and cleaved PARP-1 increased in a dose-dependent manner using a western blot assay." (PMID 36133816, 2022). "IDH1 mutations in gliomas have been shown to confer sensitivity to PARP inhibitors by reducing the production of NAD+, a molecular compound required for PARP1-mediated DNA repair." (PMID 35326540, 2022). "And inhibition of PARP-1 can improve the prognosis of glioma and promote chemoradiotherapy sensitization, which offers new ideas for treating glioma." (PMID 36092717, 2022). "In this study, we first systematically analyzed the influence of PARP-1 on DNA damage repair, prognosis, and chemoradiotherapy sensitization of glioma." (PMID 36092717, 2022). "So, it is significant to explore PARP-1’s role in the prognosis prediction of glioma patients and develop more effective treatments." (PMID 36092717, 2022).
glioma (continued). "Supplementation with the NAD+ precursor dihydronicotinamide riboside (NRH) rapidly increased NAD+ levels in GSCs and glioma cells, inducing PARP1 activation and mild suppression of replication fork progression." (PMID 34806016, 2021). "Given the elevated levels of replication stress in cancer, particularly glioma, PARP1 activation at the replication fork should be robust." (PMID 34806016, 2021). "Intriguingly, compared to U138MG glioma cells, cell death in LN18 glioma cells was accompanied by caspase-3 activation, MOMP loss, and PARP-1 cleavage." (PMID 32565808, 2020). "DPT-treated glioma cells demonstrated characteristics that fully comply with those of parthanatos, with the upregulation of PARP1, cytoplasmic accumulation of PAR polymer, and nuclear translocation of AIF." (PMID 33665167, 2020). "Results of the present work suggest that iNOS inhibition by CM544 reduces glioma cells proliferation by enhancing PARP-1 cleavage and compromising the adaptive responses of glioma cells, which are involved in chemoresistance." (PMID 30678338, 2019). "In the long run, CM544 leads to the dephosphorylation of p38 and to a massive cleavage of PARP-1, confirming the block of C6 rat glioma cell proliferation in the G1/S checkpoint and the occurrence of necrotic cell death." (PMID 30678338, 2019). "Linkage disequilibrium was also calculated for selected SNPs of PARP1 gene in meningioma and glioma patients." (PMID 31609976, 2019). "After a 6 h treatment with CM544 1.5 mM, PARP-1 cleavage increased further as compared to untreated glioma cells (131% vs. 83.3%)." (PMID 30678338, 2019). "Poly [ADP-ribose] polymerase 1 (PARP-1)-associated DNA repair is compromised in IDH-mutant cells and TMZ treatment induced greater DNA damage in IDH-mutant glioma cells." (PMID 35582280, 2019). "In our study, the results showed that flubendazole increased apoptosis among glioma cells via downregulating the expression of Bcl-2, Bcl-xl, and PARP-1, while upregulating the expression of caspase-3, caspase 6 and caspase-9." (PMID 29531815, 2018). "This plant extract also demonstrated genotoxic effects against human glioma cells by inducing DNA damage, increasing the number of cleaved PARP1-positive cells, and altering the level of γ-H2A.X-positive cells: a marker of double strand breaks in DNA." (PMID 30622675, 2018). "It was found that the percentage of cleaved PARP1-positive cells was elevated in patient-derived glioma cells and U87MG cells compared to the control cells." (PMID 30171426, 2018). "The level of cleaved PARP1-positive cells remained similar in both glioma cell lines and was about 55%." (PMID 30171426, 2018). "Differently, modified U87 glioma cells lines presenting either Tdp1 overexpression or knockout did not reveal any significant changes in the expression patterns of PARP1 gene." (PMID 29597329, 2018). "Subsequent studies unveiled a significant decrease in the mRNA and protein expression levels of Cyclin A2, Cyclin B2, and TOP2A within koORC6 P1 glioma xenograft tissues, where elevated levels of cleaved-caspase-3, cleaved-caspase-9, and cleaved-PARP-1 were detected, indicating apoptosis activation." (PMID 38971772, 2024).